JAK2 (Janus kinase 2)
Diseases named in the same sentence as JAK2 in open-access papers (continued):
Sharing a sentence is not in itself a finding about the gene and the disease.
developmental delay (1 paper, 2025). "Chromosomal microarray showed a duplication on 9p, arr[hg19] 9p24.1 (5108833-5221708) × 3, that included the JAK2 and INSL6 genes, classified as a variant of uncertain significance and not thought to be related to the patient’s developmental delay." (PMID 40869981, 2025).
diabetic retinopathy (1 paper, 2020). "It was recently observed that CXCL9 could activate Jak2/ STAT3 signalling in podocytes and correlates with retina inflammation in patients with diabetic retinopathy." (PMID 31913856, 2020).
dry-mouth (1 paper, 2025). "Quercetin mitigates salivary gland cell apoptosis and inflammation by inhibiting the LP/OB-R/JAK2/STAT3 signaling pathway, thereby providing new opportunities for alleviating dry-mouth symptoms in SS." (PMID 41255601, 2025).
eating disorder (1 paper, 2022). A broad group of psychological disorders with abnormal eating behaviors leading to physiological effects from overeating or insufficient food intake. "Moreover, the malfunction of signaling molecules in the CCK/SRC/PI3K cascade reaction with leptin/JAK2/PI3K/STAT3 signaling pathway may lead to eating disorders." (PMID 36359184, 2022).
endometrial adenocarcinoma (1 paper, 2023). "Several studies have demonstrated that in preadipocytes and endometrial adenocarcinoma cells, the GHR can activate JAK2 and then promote the MAPK pathway." (PMID 37386516, 2023).
endometrioid tumor (1 paper, 2012). A benign, borderline, or malignant epithelial tumor of the female reproductive system characterized by the presence of glands and/or cysts lined by neoplastic cells that resemble endometrial cells.
enteritis (1 paper, 2023). Inflammation of the small intestine. "The four main active compounds of MCE involved in the treatment of enteritis are SAN, CHE, PRO, and ALL, and the five core targets are HSP90AA1, MAPK1, HRAS, JAK2, and AKT1." (PMID 37200837, 2023).
enthesitis (1 paper, 2025). Inflammation at the site of insertion of ligaments, tendons, and other fibrous structures into bone. "Therefore, upadacitinib may more effectively suppress JAK2 cytokines than other JAKis; this result could explain its superior and sustained efficacy against enthesitis in PsA." (PMID 40677616, 2025).
epithelial dysplasia (1 paper, 2026). "By downregulating JAK2/STAT3 phosphorylation, KCs proliferation was inhibited and apoptosis was induced, which has therapeutic benefits for OLP epithelial dysplasia." (PMID 41983130, 2026).
Epstein-Barr virus infection (1 paper, 2021). An infection that is caused by Epstein-Barr virus. "In addition, alternative mechanisms promoting overexpression of PD-L1 and PD-L2 by RS include amplification of gene JAK2, leading to JAK2 protein overexpression and subsequent transcriptional activation of PD-L1, Epstein-Barr virus infection and activation of AP-1." (PMID 34682791, 2021).
familial chilblain lupus (1 paper, 2020). An instance of Chilblain lupus that is caused by an inherited modification of the individual's genome. "JAK inhibition with tofacitinib (JAK3>JAK1>JAK2), baricitinib (JAK1/2) or ruxolitinib (JAK1/2) showed efficacy for familial chilblain lupus in human case studies and small clinical trials." (PMID 32714331, 2020).
gallbladder adenocarcinoma (1 paper, 2016). A carcinoma that arises from glandular epithelial cells of the gall bladder. "In a v-Src-transformed human gallbladder adenocarcinoma cell line, JAK2 is constitutively activated, suggesting that Src is involved in JAK activation." (PMID 26956044, 2016).
gliosarcoma (1 paper, 2018). A rare histological variant of glioblastoma (WHO grade IV) characterized by a biphasic tissue pattern with alternating areas displaying glial and mesenchymal differentiation (WHO). "We further validated this finding with assays demonstrating a significantly lower IC50 of the JAK2-inhibitor ruxolitinib compared to TMZ in both gliosarcoma cultures, while the IC50 of ruxolitinib was modestly higher than TMZ in GBM1." (PMID 29416795, 2018). "STAT4 is phosphorylated by JAK2, and we confirmed that the JAK2-inhibitor ruxolitinib was more cytotoxic at comparable micromolar concentrations than TMZ in two gliosarcoma cultures, meriting further exploration in preclinical models." (PMID 29416795, 2018).
Hashimoto thyroiditis (1 paper, 2022). An autoimmune disorder caused by the production of autoantibodies against thyroid tissue. "In Hashimoto’s thyroiditis, T CD4+ lymphocytes, under the action of antigen presenting cells (APCs), activate RORγt through the JAK2/STAT3 pathway and differentiate into Th17 cells." (PMID 36339447, 2022).
hematoma (1 paper, 2024). A hematoma is a collection of blood from a vascular structure into an extravascular space. "Immunofluorescence tests showed significantly higher fluorescence intensity of JAK2 and STAT3 in the blood 10 μL group on day 7 compared to the control and STAT3‐IN‐12 groups (P < 0.001), suggesting the activation of the JAK‐STAT signaling pathway after hematoma in the mPFC." (PMID 38946585, 2024).
hepatopulmonary syndrome (1 paper, 2020). Hepatopulmonary syndrome (HPS) is a lung disease characterized by widening of arteries and veins (dilatation) in the lungs in people who have chronic liver disease. "In a rat model of the hepatopulmonary syndrome, miR-101 inhibited the JAK2/STAT3 signaling pathway by targeting JAK2, thereby inhibiting the proliferation of PMVECs." (PMID 32635504, 2020).
Hypoglycemia (1 paper, 2025). A decreased concentration of glucose in the blood. "This is highly relevant, as JAK2-driven PV models demonstrated profound metabolic dysregulation, including hypoglycemia and cachexia, supporting the concept that these malignancies exhibit metabolic alterations that may be therapeutically targeted." (PMID 41003014, 2025).
idiopathic inflammatory myopathy (1 paper, 2025). Idiopathic form of inflammatory myopathy. "In addition, we reviewed previous studies on the treatment of adult DM with ruxolitinib, and summarized reports of the JAK2 V617F mutation in adult idiopathic inflammatory myopathy." (PMID 40574830, 2025).
immunotoxicity (1 paper, 2022). "Aflatoxin B1 can induce immunotoxicity in 3D4/21 cells via the DNA methyltransferase-mediated JAK2/STAT3 pathway." (PMID 36552567, 2022).
inflammatory breast carcinoma (1 paper, 2024). An advanced, invasive breast adenocarcinoma characterized by the presence of distinct changes in the overlying skin. "Intriguingly, a recent study of inflammatory breast cancer demonstrated a JAK2/STAT3 signaling axis that conferred chemoresistance and EMT, consistent with our findings of CAF2-regulated malignant cell traits." (PMID 38388711, 2024).
intestinal obstruction (1 paper, 2026). Blockage of the normal flow of the intestinal contents within the bowel. "Case Presentation: We report the case of a 25-year-old man with previously diagnosed, JAK2-negative PV who presented with acute abdominal pain, nausea, vomiting, abdominal distension, and absence of stool and flatus, consistent with clinical features of intestinal obstruction." (PMID 42029457, 2026).
intestinal tumors (1 paper, 2021). "In summary, MLKL exhibits a suppressive effect in the progression of intestinal tumors by regulating the IL-6/JAK2/STAT3 axis." (PMID 33767595, 2021).
kidney stone (1 paper, 2025). "Given the well-established role of IGF1R in influencing STAT3 phosphorylation, this study focused on the regulation of downstream LDHA by JAK2/STAT3 signaling axis and its role in kidney stone formation." (PMID 39744436, 2025).
leiomyoma (1 paper, 2023). A well-circumscribed benign smooth muscle neoplasm characterized by the presence of spindle cells with cigar-shaped nuclei, interlacing fascicles, and a whorled pattern. "To further understand the effect of adipocyte on JAK2/STAT3 signaling in leiomyoma development, we cocultured primary and immortalized myometrium and leiomyoma cells with adipocytes and treated the leptin." (PMID 36771423, 2023). "Additionally, inhibitors of MAPK/ERK, JAK2/STAT3, and PI3k/AKT leptin receptor pathways are more effective in leiomyoma cells cocultured with adipocytes." (PMID 36771423, 2023). "Furthermore, adipocyte coculture and leptin treatment increases leiomyoma cells growth through activation of MAPK/ERK, JAK2/STAT3, and PI3k/AKT signaling pathways." (PMID 36771423, 2023).
male reproductive system diseases (1 paper, 2023). "Thus, the JAK2/STAT3 and Keap1/Nrf2 pathways and their components can be considered therapeutic targets for drug design to manage male reproductive system diseases." (PMID 37759514, 2023).
metastatic cancers (1 paper, 2022). A carcinoma which has spread from the original site of growth to another anatomic site. "In line with the observations of HeLa cells, deletion of JAK2 in human cancers was associated with increased genome alterations (pan-cancer, n = 10939), and alterations of JAK2, including deep deletion, amplification, and mutations, were found in a spectrum of human metastatic cancers." (PMID 35851582, 2022).
mycoses (1 paper, 2025). "Reported endemic mycoses associated with JAK1/JAK2 inhibitors and clinical presentations." (PMID 41164159, 2025). "Clinicians should be made aware of the heightened risk of relapse of fungal infections in patients on JAK1 and JAK2 inhibitors." (PMID 41164159, 2025).
myxofibrosarcoma (1 paper, 2023). A malignant fibroblastic neoplasm arising from the soft tissue. "These clues further infer a question of whether, in a positive feedback loop, overproduced CSF2 in myxofibrosarcoma cells depends on nuclear PAK1 to invigorate the activity of JAK2/STAT5B cascade." (PMID 37564209, 2023).
myxoma (1 paper, 2024). A benign soft tissue neoplasm characterized by the presence of spindle and stellate cells, lobulated growth pattern, and myxoid stroma formation. "The secretion of IL-6 from the myxoma cells was significantly inhibited by the treatment with AG490 (JAK2 inhibitor, 100 μmol/L), piceatannol (STAT1/3 inhibitor, 100 μmol/L), LLL12 (STAT3 inhibitor, 10 μmol/L), and Ly294002 (PI3K/Akt inhibitor, 30 μmol/L)." (PMID 38396907, 2024).
nasal polyp (1 paper, 2021). "The levels of p-JAK2 for the nasal polyp tissues were measured in each group." (PMID 34356683, 2021). "Our results found that the p-JAK2 have a high level in CRS, particularly in severe nasal polyps patients, discovered not only in the ELISA assay but also in IHC staining." (PMID 34356683, 2021).
necrotizing enterocolitis (1 paper, 2024). Necrotizing enterocolitis (NEC) is a devastating disease that affects mostly the intestine of premature infants. "Furthermore, JMJD3 inhibition improved necrotizing enterocolitis (NEC) by attenuating the inflammatory response and ameliorating intestinal injury via the NF-κB and JAK2/STAT3 pathways in NEC mice." (PMID 38245781, 2024).
osteonecrosis (1 paper, 2024). A none disease characterized by death of bone tissue due to a lack of blood supply. "EP300, TRAF6, STAT1, JAK1, CASP8, and JAK2 have exhibited significant differences in SANFH (spontaneous osteonecrosis of the femoral head)." (PMID 38204239, 2024). "In conclusion, EP300, TRAF6, STAT1, JAK1, CASP8, and JAK2 exhibit significant differences in SANFH (spontaneous osteonecrosis of the femoral head)." (PMID 38204239, 2024).
osteopetrosis (1 paper, 2021). Osteopetrosis, also known as marble bone disease, is a descriptive term that refers to a group of rare, heritable disorders of the skeleton characterized by increased bone density on radiographs. "In our study, Oc-JAK2–KO mice did not display an increase in bone mass or any stigmata of osteopetrosis; therefore, it is unlikely that growth restriction occurred as a result of impairment in the traditional osteoclast function in bone resorption." (PMID 33682794, 2021).
pelvic inflammatory disease (1 paper, 2024). Pelvic inflammatory disease (PID) is an acute or chronic inflammation in the pelvic cavity. "The mechanism by which modified Hongteng Baijiang decoction improves endometrial receptivity in sequelae of pelvic inflammatory disease rats may be related to the LIF/JAK2/STAT3 signaling pathway and gut microbiota." (PMID 38896093, 2024).
penile cancer (1 paper, 2024). A primary or metastatic malignant neoplasm that affects the penis. "During tumorigenesis phase of penile cancer, the expression evolution of JAK-STAT-SOCS1 axis was characterized by the upregulation of JAK2, STAT1, STAT2, STAT3 and STAT4." (PMID 38774752, 2024).
pituitary tumor (1 paper, 2023). A benign or malignant neoplasm affecting the pituitary gland. "Moreover, the IL-6/JAK2/STAT3 pathway seems to be involved in the invasiveness of pituitary tumors by increasing the expression of MMP-9." (PMID 37958702, 2023).
placental cancer (1 paper, 2019). "The ovarian and placental cancer cell line selective inhibitors included actinomycin D (IC50 = 0.78 ± 0.222 μM; SI >100), a DNA intercalator and common drug for GTD, and fedratinib (IC50 = 13.1 ± 7.51 μM; SI >100), a JAK2 inhibitor." (PMID 30576957, 2019).
plasma cell leukemia (1 paper, 2020). An aggressive plasma cell neoplasm characterized by the presence of neoplastic plasma cells in the peripheral blood. "Here, we report a case of a patient with a recent diagnosis of a JAK2 V617F positive MPN who presented with a new diagnosis of plasma cell leukemia." (PMID 32974181, 2020).
prediabetes (1 paper, 2023). "Results of this study and previous results showed an overexpression of Toll-like receptors (TLR4 and 6), Janus kinase 2 (JAK2) and Vascular endothelial growth factor A (VEGFA) in prediabetes patients." (PMID 37457235, 2023).
protein c deficiency (1 paper, 2024). Protein C deficiency is a disorder that increases a person's risk to develop abnormal blood clots due to a deficiency of the Protein C, a protein in the body that prevents blood clotting. "Mutations in the PROC gene leading to protein C deficiency, as well as those in the JAK2 gene, had been shown to be specifically associated with CVT." (PMID 38886735, 2024).
renal dysfunction (1 paper, 2026). "We describe a 73-year-old woman with PV harboring a JAK2 V617F mutation who developed hematuria, proteinuria, and renal dysfunction." (PMID 42211688, 2026).
Richter syndrome (1 paper, 2015). Transformation of chronic lymphocytic leukemia into aggressive non-Hodgkin's lymphoma, usually diffuse large B-cell lymphoma (immunoblastic or centroblastic variant). "However, considering the heterogeneity of the disease and the presence of particularly aggressive transformation forms of B-CLL, such the Richter's syndrome, it will be of great interest to perform a systematic genetic analysis of JAK2 mutations in B-CLL." (PMID 26413812, 2015).
sarcopenia (1 paper, 2024). Progressive decline in muscle mass due to aging which results in decreased functional capacity of muscles. "Our results suggested that BDNF, JAK2, RhoC, Myh6, Stat5a, Tnnc1, and other genes may mediate the beneficial effects of exercise on sarcopenia through these pathways." (PMID 39309455, 2024). "Transcriptomic analysis identified BDNF, JAK2, RhoC, Myh6, Stat5a, and Tnnc1 as core target genes that may mediate the effects of different exercise intervention stimuli through the JAK-STAT, cGMP-PKG, and Rap1 pathways to improve the skeletal muscle phenotype of sarcopenia." (PMID 39309455, 2024).
schistosomiasis (1 paper, 2023). An infectious disease caused by parasitic trematodes of the genus Schistosoma that colonize human blood vessels and release eggs that can cause granulomatous reactions leading to acute (swimmer's itch or acute schistosomiasis syndrome) or chronic disease. "Hepatic injury caused by schistosomiasis was exacerbated by the accumulation of reactive oxygen species, which activated JAK2 and STAT3." (PMID 37339146, 2023).
Secondary acute myeloid leukemia (1 paper, 2014). "Secondary acute myeloid leukemia (sAML) is a known complication of JAK2-V617F+ MPNs and bears a poor prognosis." (PMID 24744787, 2014).
seminoma (1 paper, 2025). A radiosensitive malignant germ cell tumor found in the testis (especially undescended), and extragonadal sites (anterior mediastinum and pineal gland). "Most of these focal events occurred in both subtypes but were more significantly targeted in seminomas, except 9p24.3/JAK2 deletion, exclusively found in seminomas." (PMID 40568177, 2025).
sensitization (1 paper, 2014). "SNPs in or near JAK2, CNOT6, MAML1, CD40, IL-4R, and IL-5RA genes were associated with allergic sensitization and SNPs in or near JAK1, JAK3, IL5RA, FCER1A, and ADAM33 genes were associated with cockroach sensitization." (PMID 25505553, 2014).
serous retinal detachment (1 paper, 2026). "A case report of baricitinib, a selective JAK1 and JAK2 inhibitor, use in a patient with ocular and systemic features of seronegative RA showed resolution of anterior chamber cell, corneal infiltrates, vitreous opacity, and serous retinal detachment at 3 month follow-up." (PMID 41198980, 2026).
skin aging (1 paper, 2019). The gradual irreversible changes in structure of skin that occur as a result of the passage of time.. "Taken together, our findings provide evidence that quercetin attenuates UV-stimulated MMP-1 and COX-2 expressions via direct inhibition of JAK2 and PKCδ kinase activities, thereby preventing UV-induced skin aging." (PMID 31652815, 2019). "Examination of the molecular mechanism revealed that quercetin exerts protective effects against UV-mediated skin aging via directly targeting PKCδ and JAK2." (PMID 31652815, 2019).
somatic erythrocytosis (1 paper, 2021). "Primary acquired erythrocytosis, i.e., somatic erythrocytosis (OMIM ID: 133100), is the consequence of somatic genetic variants in Janus kinase 2 (JAK2) gene and SH2B adaptor protein 3 (SH2B3) gene, which lead to constant activation of EPO signaling pathway." (PMID 34349782, 2021).
spinal cord injury (1 paper, 2025). Penetrating and non-penetrating injuries to the spinal cord resulting from traumatic external forces (e.g., WOUNDS, GUNSHOT; WHIPLASH INJURIES; etc.). "In the spinal cord injury (SCI) model, IL-6-induced activation of the JAK2/STAT3 signaling pathway in spinal dorsal horn microglia and astrocytes contributes to the progression of pain." (PMID 40093024, 2025).
Stillbirth (1 paper, 2023). Death of the fetus in utero after at least 22 weeks of gestation. "The stillbirth occurred in a patient who was diagnosed with JAK2‐mutated ET late in the second trimester of pregnancy and started aspirin at 24 weeks." (PMID 36819152, 2023). "Three of the losses occurred in pregnancies in which JAK2 was the driver mutation (two first trimester losses and the stillbirth), and two losses occurred in pregnancies with triple‐negative MPN (one first trimester loss and the second trimester loss)." (PMID 36819152, 2023).
synovitis (1 paper, 2022). Inflammation of a synovial membrane. "Our results show significant correlation between synovial IL-6, JAK2, STAT1; blood IL-6 and lympho-myeloid synovitis." (PMID 36465908, 2022).
T-cell neoplasms (1 paper, 2013). "MAC-1/2A/2B are the first cell lines shown to carry a JAK2 translocation, and the extreme C-terminal placement of the breakpoint within JAK2 clusters with those previously reported in T-cell neoplasms." (PMID 23372669, 2013).
tendinopathy (1 paper, 2025). "In summary, macrophage PTP1B was shown to regulate mitochondrial dynamics via the JAK2/STAT3-OPA1 axis and trigger inflammation through activation of the cGAS/STING pathway, representing a key mechanism underlying the progression of tendinopathy." (PMID 41132674, 2025).